G6PD (glucose-6-phosphate dehydrogenase)
Diseases named in the same sentence as G6PD in open-access papers (continued):
Sharing a sentence is not in itself a finding about the gene and the disease.
anemia (continued). "These include, among others, the parasite species, level of parasitemia, age of host, host genetic factors (e.g., coexisting RBC polymorphisms like hemoglobinopathies, G6PD), and nonmalarial causes of anemia (e.g., infections, malnutrition)." (PMID 25285308, 2013). "We found evidence of an interaction of treatment group with parasite density, suggesting that failure to rapidly eliminate parasitaemia may have explained the anaemia after CD in G6PD normal subjects." (PMID 21666744, 2011). "Incidence of severe anaemia after treatment according to G6PD genotype." (PMID 21666744, 2011). "The information regarding the presence of conditions such as thalassemia (which is another rare disease in Korea), anemia, and a high reticulocyte count, which may have affected the G6PD test results, as well as whether the parents of pediatric patients underwent screening, was also limited." (PMID 37176619, 2023). "A G6PD-deficient individual with baseline haemoglobin level x g/dL who received 0.25 mg/kg of primaquine had a similar risk of severe anaemia (Hb < 7 g/dL) to an individual who had not received primaquine with a 1 g/dL lower (x − 1 g/dL) baseline haemoglobin level." (PMID 36109733, 2022). "Besides, mild to moderate anaemia was observed in 41.2% (7 of 17 cases) of patients with G6PD MahidolG487A and 16.7% (36 of 215 cases) of patient with wildtype G6PD (non-common SEA mutation) (OR = 3.48; CI%: 1.24 – 9.75, p = 0.018)." (PMID 36038921, 2022). "Dapsone may also cause dose-dependent anemia, though the incidence of anemia in heart transplant patients with normal G6PD activity on dapsone is not well characterized." (PMID 36362606, 2022). "Health workers did not explain the risk of anemia to patients when taking certain antimalarials nor how G6PD testing could help improve the safety of vivax treatment." (PMID 33396538, 2020). "However, these tests do not accurately define G6PD activity in females, potentially exposing women with intermediate G6PD activity to the risk of severe anemia, hemolysis and other health impacts." (PMID 30184203, 2019). "Previously published data have demonstrated that sickle red blood cells produce twice as much reactive oxygen species (ROS) suggesting that co-inheritance of sickle cell disease (SCD) and glucose 6-phosphate dehydrogenase (G6PD) enzymopathy could lead to more severe anaemia during sickling crises." (PMID 29021902, 2017). "Multivariate regression revealed a significant association of moderately and severely deficient G6PD genotypes with haemoglobin levels according to the baseline data (p < 0.0001; G6PD heterozygous: p < 0.0001; G6PD deficient: p = 0.009), but not with severe malarial anaemia (p = 0.66)." (PMID 27388012, 2016). "Furthermore, G6PD activity is conventionally expressed as international units per gram Hb, and in populations where anemia is common, the resulting estimation of enzymatic activity might be falsely increased by a low concentration of Hb in the blood." (PMID 25646252, 2015). "Age may bear upon risk of anemia, and could possibly account for the trend observed, but when G6PD activity was plotted as a function of age, no trends emerged." (PMID 25746733, 2015). "This mutation causes a moderate to mild reduction of G6PD activity to 5–32% of wild-type activity in healthy individuals, while most patients with the 487G>A variant are usually asymptomatic (with no severe anemia)." (PMID 26226515, 2015). "This may explain the significantly higher proportion of G6PD-deficent individuals for these different types of anaemia compared to the non-deficient in the present study." (PMID 25406667, 2014). "However, we could not find any statistical differences between IDA patients with mild, moderate and severe anemia and healthy subjects regarding plasma G6PD and 6PGD activities in our study." (PMID 25097522, 2014).
anemia (continued). "Artesunate may cause a temporary suppression of reticulocytosis which does not translate into anaemia, but would not explain the differential effect in G6PD-deficient subjects." (PMID 19112496, 2008). "However, G6PD’s effect on maternal anaemia after IPTp intake could be negligible." (PMID 36303165, 2022). "Additional characterization of red blood cells were not performed although certain red blood cell conditions such as anaemia, which causes a reduction in the volume of older G6PDd RBC’s and an increase in reticulocytes, could result in anaemic G6PDd child exhibiting near normal G6PD enzyme activity." (PMID 27456336, 2016). "Even though mean haemoglobin (Hb) levels were statistically significantly higher in the G6PD deficient than G6PD normal at baseline (P<0.001), on the average, study women in both groups had mild anaemia and the 0.5 g/dl difference may not have much clinical significance." (PMID 26327623, 2015). "Both anaemia and haemoglobinuria may go unnoticed or unreported, and the frequency of adverse events in G6PD deficient subjects is diluted by the much larger numbers of G6PD normal subjects in whom AHA does not occur." (PMID 23237606, 2012). "In the context of recurrent anemia and the absence of prior newborn screening, an evaluation of glucose-6-phosphate dehydrogenase (G6PD) enzyme activity was performed." (PMID 41041388, 2025). "The majority of respondents (336; 73.2%) had never heard about G6PD anemia, but 377 (82.1%) participants were familiar with fava bean anemia." (PMID 38125694, 2023). "One small study observed dapsone-related anemia in kidney, lung, liver, and heart transplant recipients though G6PD activity was not documented in all patients." (PMID 36362606, 2022). "Although mutations in G6PD and HBA2 are associated with anemia and human disease, SEC14L4 and MYO9B are not previously known to affect RBC function." (PMID 34793330, 2022). "Most of the G6PD have neither anemia nor evidence of increased RBC destruction, nor an alteration in blood morphology, although a modest shortening of RBC survival can be demonstrated by isotopic techniques." (PMID 31703724, 2019). "Yet, co-inheritance of G6PD with α-thalassemia or HbE trait did not affect the hematological parameters or induce more severe anemia." (PMID 28531196, 2017). "The vast majority of cases for two of these causes are asymptomatic sequelae that have no YLDs associated with them: genital herpes with no active lesions, and G6PD trait that does not result in anaemia." (PMID 28919117, 2017). "Anaemia prevalence (defined in this case as Hb levels under 10g/dl) was not significantly different between G6PD classes (p = 0.072)." (PMID 23782846, 2013). "An enzyme, such as Glucose-6-phosphate dehydrogenase (G6PD) could play a role as its X-linked gene locus is at Xq28 and it has a great multiplicity of alleles that are associated in their deficiency with nonspherocytic hemolytic anemia, and anemia is a likely risk factor for SIDS." (PMID 20049339, 2009). "Anaemia is a known confounder of G6PD screening, but was not adjusted for in this study." (PMID 28376871, 2017). "As a confirmation, in the experience with the FST in the hematology laboratory of the SMRU, it has been noted before that samples from G6PD-normal anemic subjects (especially pregnant women) do tend to show a brighter fluorescence compared with G6PD-normal subjects without anemia." (PMID 25646252, 2015). "We conducted this study to determine the erythrocyte glucose-6-phosphate dehydrogenase (G6PD) activity level in patients with end-stage renal disease (ESRD) on maintenance hemodialysis (HD) and to determine the effect of hemodialysis adequacy on G6PD activity levels and its impact on anemia." (PMID 25261071, 2014). "WRA with G6PD had more than double the odds of anaemia, and WRA with haemoglobinopathies had more than 6.1 times higher odds of anaemia relative to women without these conditions." (PMID 32153098, 2022).
anemia (continued). "Dapsone-related anemia has also been observed in non-SOT patients, up to 87% in stem cell transplant recipients with normal G6PD activity, 4% in patients with HIV, and 25% of patients with leprosy." (PMID 36362606, 2022).
vivax malaria (111 papers, 2010 to 2025). "If a 2-week radical curative regimen was shown to be safe in G6PD-deficient vivax malaria patients, this would reduce the duration of treatment by a factor of 4 (currently, an 8-week regimen is recommended)." (PMID 39992119, 2025). "This is contrary to a study on the Asian population that found that men were more protected against vivax malariae because of the haemolytic effect of G6PD, its X-linked genetics, and a positive selection of its variant." (PMID 40951120, 2025). "Wider use of G6PD diagnostics for the safe administration of radical cure will be critical to reduce relapse and the transmission of vivax malaria in high-risk populations." (PMID 38728310, 2024). "Routine G6PD testing is mostly done at the level of health centres, but people at risk of vivax malaria tend to live far from these facilities; consequently, only a fraction have access to routine testing." (PMID 36986323, 2023). "Complete cure of vivax malaria is hindered by the risk of hemolysis in glucose-6-phosphate dehydrogenase deficient (G6PDd) individuals post primaquine and other 8-aminoquinoline antimalarials." (PMID 36709318, 2023). "A high prevalence of G6PD c202G > A and c.376A > G and Duffy variants is observed in Manaus, an endemic area for vivax malaria." (PMID 35527254, 2022). "Molecular genotyping of G6PD and Duffy variants was performed in 225 unrelated patients (97 with uncomplicated and 128 with severe vivax malaria) recruited at a Reference Centre for Infectious Diseases in Manaus." (PMID 35527254, 2022). "A high prevalence of G6PD c202G > A and c.376A > G and Duffy variants is observed in Manaus, Amazonas state, Brazil, principally in severe vivax malaria patients." (PMID 35527254, 2022). "Unfortunately, in many regions, G6PD testing is unavailable so the practitioner treating vivax malaria is faced with a dilemma—to give radical cure “at risk,” or to err on the side of safety and not give it." (PMID 33891587, 2021). "The proportion of patients with vivax malaria at risk of serious haemolysis with G6PD Med in these studies is nearly four times lower than would be predicted from gene frequencies in the healthy population." (PMID 33543710, 2021). "There is also evidence for protection against vivax malaria from the moderate severity G6PD Mahidol variant." (PMID 33543710, 2021). "We fitted a Bayesian statistical model to observed G6PD Med allele frequencies in 999 Pashtun patients presenting with acute Plasmodium vivax malaria and 1408 population controls." (PMID 33543710, 2021). "Glucose-6-phosphate dehydrogenase (G6PD) deficiency greatly hinders Plasmodium vivax malaria radical cure and further elimination due to 8-aminoquinolines-associated hemolysis." (PMID 34003840, 2021). "At presentation of acute Plasmodium vivax malaria, glucose-6-phosphate dehydrogenase deficient (G6PDd) males have low G6PD activity that is unrelated to baseline reticulocyte counts; they were all detected by the qualitative fluorescent spot test." (PMID 34495956, 2021). "The Duffy (gp-FY; CD234) gene is the fourth red blood cell (RBC) gene after thalassemia, sickle cell anaemia and glucose-6-phosphate dehydrogenase (G6PD) associated with resistance to Plasmodium species albeit with particular protection against vivax malaria." (PMID 32590997, 2020). "Primaquine is an approved radical cure treatment for Plasmodium vivax malaria but treatment can result in life-threatening hemolysis if given to a glucose-6-phosphate dehydrogenase deficient (G6PDd) patient." (PMID 32004348, 2020). "Treatment of Plasmodium vivax malaria with primaquine poses a potential risk of mild to severe acute haemolytic anaemia in G6PD deficient people." (PMID 31590661, 2019). "It requires to have a test of glucose-6-phosphate dehydrogenase (G6PD) deficiency before treatment of each vivax malaria patient by primaquine therapy." (PMID 30700970, 2019).
vivax malaria (continued). "In vivax malaria infected patients these proportions will be lowered by any protective effect against P. vivax conferred by G6PD deficiency." (PMID 29677199, 2018). "Studies in the Brazilian Amazon (Manaus) among local populations demonstrated a significant protection of vivax malaria in the G6PD-deficient men enrolled in these studies, independently of their age." (PMID 30286752, 2018). "That problem excludes a large number of people from safe and effective treatment of the latent stage of vivax malaria: the G6PD deficient, pregnant or lactating women, and young infants." (PMID 29357870, 2018). "Taken together, the estimated frequencies of these primaquine ineligibles due to G6PD toxicity or impaired CYP2D6 activity composed over 35% of the populations at risk of vivax malaria." (PMID 29357870, 2018). "Primaquine is essential for the radical cure of vivax malaria, however its broad application is hindered by the risk of drug-induced haemolysis in individuals with glucose-6-phosphate-dehydrogenase (G6PD) deficiency." (PMID 28797255, 2017). "8-aminoquinolines (primaquine and tafenoquine) are used for the radical curative treatment of Plasmodium vivax malaria and can cause haemolysis in G6PD deficient subjects." (PMID 28852037, 2017). "Recently revised World Health Organization (WHO) recommendations suggest to test for G6PD deficiency before radical cure of vivax malaria." (PMID 26849445, 2016). "Second, G6PD deficiencies need to be monitored, and chloroquine/primaquine used for 14 days can be radically cure vivax malaria." (PMID 27716435, 2016). "Perhaps the greatest impediment to the control and elimination of vivax malaria in Indonesia is the problem of primaquine toxicity in glucose-6-phosphate dehydrogenase–deficient (G6PDd) patients." (PMID 27708185, 2016). "The seven common G6PD variants were investigated by DiaPlexC kit in blood samples obtained living in vivax malaria endemic regions in the ROK." (PMID 24853873, 2014). "This study evaluated G6PD enzymatic activity and the prevalence of G6PD variants in individuals living in the vivax malaria endemic Yeon-cheon and Pa-ju regions of the ROK." (PMID 24853873, 2014). "In this study, 98 non-G6PD-deficient adult patients with vivax malaria in Thailand were randomized to AL or chloroquine, both administered with primaquine." (PMID 22216359, 2011). "Analyses of a case-control study among Afghan refugees in Pakistan find that a G6PD (glucose-6-phosphate dehydrogenase) “Mediterranean” type deficiency confers substantial protection against Plasmodium vivax malaria." (PMID 20520804, 2010). "To develop shorter primaquine dosing regimens with acceptable safety profiles for G6PD-deficient patients with vivax malaria, we compared ascending primaquine dose regimens with a single high dose of primaquine (45 mg) in hemizygote G6PD-deficient male volunteers in Thailand." (PMID 39992119, 2025). "Scaled availability of point-of-care G6PD diagnostic kits for rural tropical regions, which suffer the largest burden of vivax malaria, will protect individuals vulnerable to 8-aminoquinolone drug-induced adverse events and enable individuals with normal G6PD levels to receive curative treatment." (PMID 38728310, 2024). "However, this class of 8-aminoquinolines can cause hemolysis in individuals with low G6PD enzyme activity, which presents an obstacle to the global implementation of drug delivery against vivax malaria." (PMID 37513742, 2023). "G6PD-deficient individuals are susceptible to hemolysis during oxidative stress, which can occur from exposure to certain medications, including 8-aminoquinolines used to treat Plasmodium vivax malaria." (PMID 34383774, 2021). "On the other hand, concerns regarding AHA in the absence of available G6PD testing in areas where more severe G6PD variants prevail, often result in hesitancy to prescribe PQ, leading to a continuous cycle of relapses and increased morbidity and mortality in vivax malaria patients." (PMID 34003840, 2021).